SCAPER (S-phase cyclin A associated protein in the ER)
Description:
CCNA2/CDK2 regulatory protein that transiently maintains CCNA2 in the cytoplasm.
Synonyms: ZNF291; MSTP063; Zfp291; IDDRP
Tractability: PROTAC: ubiquitination databases record sites on it; its protein half-life has been measured.
Gene: Protein-coding gene on chromosome 15 (76,347,904 to 76,905,970, reverse strand). Ensembl gene ENSG00000140386.
Subcellular location: Endoplasmic reticulum; Nucleus
Subcellular location (Human Protein Atlas): Nuclear speckles; Nucleoplasm; Basal body; Cytosol; Primary cilium; Primary cilium tip
Gene Ontology:
Molecular function: protein binding; nucleic acid binding; zinc ion binding
Biological process: retina development in camera-type eye
Cellular component: nuclear speck; nucleoplasm; cytoplasm; endoplasmic reticulum; nucleus; ooplasm; sperm head
Genetic constraint (gnomAD): Loss-of-function variants: 75 observed, 136.53 expected, observed/expected ratio (o/e) 0.55, 90% interval 0.46 to 0.67. The upper end of that interval is the gene's LOEUF score, 0.67, which puts it in group 2 of 6, group 1 being the genes least tolerant of losing a copy. Missense variants: 1,266 observed, 1,508.9 expected, observed/expected ratio (o/e) 0.84, 90% interval 0.8 to 0.88. Synonymous variants: 544 observed, 513.08 expected, observed/expected ratio (o/e) 1.06, 90% interval 0.99 to 1.14.
Gene-disease validity (ClinGen):
ClinGen rates the evidence that SCAPER causes each of these diseases.
intellectual developmental disorder and retinitis pigmentosa; IDDRP (autosomal recessive): Definitive.
Homologues: Orthologues: macaque SCAPER (98% identical), chimpanzee SCAPER (98% identical), pig SCAPER (94% identical), dog SCAPER (91% identical), guinea pig SCAPER (89% identical), mouse Scaper (88% identical), rat Scaper (88% identical), rabbit SCAPER (87% identical), tropical clawed frog scaper (71% identical), zebrafish scaper (67% identical), Drosophila melanogaster ssp3 (27% identical), Caenorhabditis elegans scpr-1 (20% identical).
Diseases named in the same sentence as SCAPER in open-access papers:
SCAPER is named in the same sentence as 10 diseases in open-access papers, as found by Europe PMC text mining. Sharing a sentence is not in itself a finding about the gene and the disease. The quoted sentences say what the papers report.
Intellectual disability (5 papers, 2023 to 2025). "On the other hand, the SCAPER gene was linked to retinitis pigmentosa and intellectual disability and the OSBPL9 gene was identified as a gene involved in canine hypoadrenocorticism." (PMID 40003092, 2025). "Some researchers (Najmabadi and coworkers) first proposed a possible involvement of the SCAPER gene in human disease by identifying a homozygous frameshift SCAPER variant as the cause of non-syndromic intellectual disability (ID) in a family from Iran." (PMID 38927727, 2024). "Mutations in the gene SCAPER (S phase Cyclin A-Associated Protein residing in the Endoplasmic Reticulum) have recently been associated with retinitis pigmentosa (RP) and intellectual disability (ID)." (PMID 38927727, 2024). "Allelic variants and mutations in SCAPER cause intellectual disability with retinitis pigmentosa in humans." (PMID 38448444, 2024). "SCAPER mutants that cause intellectual disability and retinitis pigmentosa in humans are impaired in CCR4-NOT recruitment, tubulin mRNA degradation, and microtubule-dependent chromosome segregation." (PMID 37295431, 2023).
retinitis pigmentosa (5 papers, 2023 to 2025). Retinitis pigmentosa (RP) is an inherited retinal dystrophy leading to progressive loss of the photoreceptors and retinal pigment epithelium and resulting in blindness usually after several decades. "Mutations in the gene S phase Cyclin A-Associated Protein residing in the Endoplasmic Reticulum (SCAPER) are associated with retinitis pigmentosa (RP) and intellectual disability (ID) 68-70." (PMID 40860157, 2025).
developmental delay (1 paper, 2020). "Four genes (UCP2, UCP3, SCAPER, and TSHR) are related to the body weight (HP:0004324 and HP:0004323), and four genes (C2CD3, UCP2, ZMYND11, and TSHR) are involved in modulating the phenotype of globe developmental delay (HP:0001263)." (PMID 32973871, 2020).
cancer (1 paper, 2023). A tumor composed of atypical neoplastic, often pleomorphic cells that invade other tissues. "Endocrine system development and cancer growth-related ceRNA regulation are found in TNBC; HOXA5, SCAPER, PAK6, PBX1, PITX1, and ALOX15B are the relevant genes involved; and hsa-miR-296-5p, hsa-miR-185-5p, hsa-miR-7851-3p, hsa-miR-3187-3p, and hsa-miR-10396b-5p are the relevant miRNAs involved." (PMID 37483500, 2023).
genetic diseases (1 paper, 2023). "The findings assign molecular functions to the previously obscure proteins SCAPER and CNOT11, provide mechanistic insight into genetic diseases caused by SCAPER mutations, and provide a detailed view of how a nascent protein can selectively control the degradation of its encoding mRNA." (PMID 37295431, 2023).
SCAPER also shares sentences with these, for which no sentence is quoted: Bardet-Biedl syndrome (1 paper); cholangiocarcinoma (1); Joubert syndrome (1); major depression (1); retinal disease (1).